RAD51 (RAD51 recombinase)
Diseases named in the same sentence as RAD51 in open-access papers (continued):
Sharing a sentence is not in itself a finding about the gene and the disease.
ovarian carcinoma (continued). "High RAD51 expression indicated unfavorable survival outcomes and resistance to platinum, taxane, and PARP inhibitors in ovarian cancer." (PMID 33952262, 2021). "Notably, RAD51 inactivating mutations are absent in familial breast and ovarian cancer." (PMID 34316706, 2021). "Taken together, RAD51 confers drug tolerance, including platinum, taxane, and PARP inhibitors, in ovarian cancer." (PMID 33952262, 2021). "Increased RAD51 expression remarkably correlated with reduced drug responsiveness to platinum, taxane, and PARP inhibitors in ovarian cancer." (PMID 33952262, 2021). "For example, Aurora-A suppresses BRCA2-expressing ovarian cancer cells while its silencing restores the level of BRCA2 and increases the number of DNA repair foci of both BRCA2 and Rad51 after γ-irradiation." (PMID 32550913, 2020). "Similar findings have been reported in ovarian cancers: HRR was upregulated when Pol θ expression was inhibited, while Pol θ expression blocks RAD51-mediated HRR due to RAD51 binding motifs in Pol θ." (PMID 31552165, 2019). "In cultures of ovarian cancer cells, we have previously shown that HRR function, based upon RAD51 foci quantification, correlated with growth inhibition ex vivo induced by rucaparib (a PARPi) and 12-month survival following platinum chemotherapy." (PMID 30871186, 2019). "Significant expression changes were also confirmed by RT-qPCR for some genes involved in homologous (HR) and non-homologous end joining (NHEJ) DNA damage-repair mechanisms in ovarian cancer, such as XRCC1 in EOC-CC1, and XRCC4, RAD51 and BRCA2 in OSPC2." (PMID 28482906, 2017). "To investigate the DNA repair response during this period we used immunofluorescence to investigate RAD51 DNA repair foci following 24 h of 6 μM cisplatin treatment in A375 melanoma, PEO4 ovarian cancer cells and MRC5v1 immortalised fibroblasts." (PMID 29254481, 2017). "The BRCA2 revertant ovarian cancer cell line, PEO4, showed a smaller but still significant (P = 0.001) 2-fold increase in RAD51 foci after cisplatin treatment." (PMID 29254481, 2017). "The RAD51 levels are higher in ovarian cancer cells than in FTE-187 cells, and berberine treatment led to a significant downregulation of RAD51 in A2780, HEY and HO8910 cells." (PMID 28981112, 2017). "Therefore, both PRIM2 loss and RAD51 downregulation in HGS cancer may result in utilization of the error-prone repair pathway (e.g. non-homologous end joining) and may contribute to the extensive rearrangements found in HGS ovarian cancer." (PMID 25916844, 2015). "Similar results were observed with patient-derived ovarian cancer cells, i.e. increased sensitivity to IGF-1Rki of cells having low HR functionality as compared to cells capable of forming increased level of RAD51 foci formation." (PMID 26510816, 2015). "RAD51 gene plays an important role in the pathogenesis of squamous cell carcinoma of the head and neck (SCCHN), colorectal cancer, ovarian cancer and acute leukaemia." (PMID 24457040, 2014). "17-AAG downregulated protein levels of BRCA1 and RAD51 in 36M2 and RAD51 alone in SKOV3 ovarian cancer cell lines." (PMID 24798692, 2014). "In ovarian cancer, GRB2 maintains replication fork stability by inhibiting RAD51 ATPase activity, preventing cytosolic DNA release that activates cGAS‐STING; GRB2 deficiency allows PARP inhibitors (PARPis) to induce DNA fragment release and enhance antitumour immunity." (PMID 41350246, 2025). "Recent studies have demonstrated that KLF5 forms a transcriptional complex with EHF and ELF3, remodeling RAD51 transcription to enhance the homologous recombination repair (HRR) pathway in ovarian cancer cells, thereby promoting ovarian cancer progression and PARPi resistance." (PMID 40307891, 2025). "Because NEAT1 knockdown decreased RAD51 levels and HR ability, we wondered whether knockout of NEAT1 sensitized ovarian cancer cells to Olaparib." (PMID 38356722, 2024).
ovarian carcinoma (continued). "Mutations in other genes involved in DNA repair, such as PALB2, RAD51, and CHEK2 may be expressed in ovarian cancers." (PMID 37958970, 2023). "As measured by RAD51 focus formation, restoration of HR is shown to be acquired before restoration of fork protection in a panel of isogenic olaparib-resistant BRCA1 mutant ovarian cancer cells." (PMID 35886427, 2022). "Thus, we next examined the expression of RAD51 and p21 under CHD4 knockdown in two ovarian cancer cells, TOV21G, and JHOC5." (PMID 34161330, 2021). "In conclusion, the LaCl3 could attenuate the DDP resistance of ovarian cancer cells via inhibiting PI3K/Akt pathway, downregulated RAD51 to inhibit DNA repair, and eventually promoted cell apoptosis due to DDP." (PMID 34977076, 2021). "Second, an EMSY-amplified ovarian cancer cell line has normal RAD51 focus formation in response to DNA damage and RAD51 focus formation was not affected by knockdown of EMSY." (PMID 34440403, 2021). "MiR-509-3 could impair the proliferation, migration, and invasion ability but enhance the sensitivity to Olaparib of ovarian cancer cell in vitro and in vivo by directly targeting HMGA2 and RAD51." (PMID 32005272, 2020). "We knocked down EMSY in OVCAR3, an ovarian cancer cell line with EMSY amplification, and measured RAD51 foci formation upon treatment with camptothecin (CPT), an inhibitor that targets DNA topoisomerase I resulting in collapse of the replication fork and DNA double-strand breaks." (PMID 28099152, 2017). "In clear contrast, dual ATM/ATR inhibition strongly potentiates the activity of both ETs against human cervical and ovarian carcinoma cells by efficiently blocking the formation of γ-H2AX, MDC1, BRCA1 and Rad51 foci following ET-exposure thereby resulting in extensive chromosome damage." (PMID 27029031, 2016). "Conversely, ovarian cancer cells that showed increased Rad51 foci, and thus had adequate HR, did not demonstrate cytotoxicity." (PMID 27642590, 2016). "In PARP inhibitors-resistant but BRCA-mutant ovarian cancer cells, both fork protection functions of BRCA1/2 and HR are sequentially bypassed, and cells become increasingly dependent on ataxia telangiectasia and Rad3-related kinase (ATR) for recruitment of RAD51 onto DSB and stalled forks." (PMID 35886427, 2022). "Accordingly, many, but not all, breast and ovarian cancer panels include assessment of RAD51." (PMID 34711195, 2021). "Indeed, in ovarian cancer cell lines WRAP53β rapidly accumulates at DNA breaks, where it orchestrates the accumulation of DNA repair proteins involved in both HR and NHEJ, including RNF168, 53BP1, BRCA1 and RAD51." (PMID 26426684, 2015). "Furthermore, in ovarian cancer cell lines, WRAP53β was rapidly recruited to DNA double-strand breaks, where it orchestrated the recruitment of repair factors involved in homologous recombination and non-homologous end joining, including RNF168, 53BP1, BRCA1 and RAD51." (PMID 26426684, 2015). "As a corollary to platinum sensitivity in ovarian cancers with HRD, it is not known if the overexpression of RAD51 confers platinum resistance." (PMID 33709473, 2021). "Contrary to our expectation, the expression of RAD51 or p21, which are the known targets of CHD4 as it was shown in other cancer types, was not clearly affected by CHD4 knockdown in the ovarian cancer cells we tested." (PMID 34161330, 2021). "New findings that RAD52 is essential for cell viability in BRCA1-, PALB2- and BRCA2- and RAD51 paralog-deficient cells, but not in normal cells, suggested that RAD52 may represent an attractive therapeutic target for killing hereditary breast cancer and ovarian cancer cells." (PMID 27649245, 2016). "However, to the best of our knowledge, no study has examined RAD51 IHC expression and its time-lagged changes in FFPE samples from patients with ovarian cancer treated with PARPi." (PMID 38725623, 2024).
ovarian carcinoma (continued). "In contrast, whereas we observed a 2‐fold increase in RAD51 nuclear intensity as well as formation of nuclear foci in the HRDlow USZ‐21_LG1, neither formation of RAD51 nuclear foci nor increased RAD51 nuclear intensity were observed in the MFS and ovarian carcinoma cell models." (PMID 36779660, 2023). "This combination regimen could down-regulate the expression levels of RAD51 and BRCA as HR-related genes besides displaying a synergistic enhancement of cytotoxicity in ovarian cancer cell lines with functional and non-functional DNA repair systems." (PMID 31423128, 2019).
Fanconi anemia (92 papers, 2008 to 2025). Fanconi anemia (FA) is a hereditary DNA repair disorder characterized by progressive pancytopenia with bone marrow failure, variable congenital malformations and predisposition to develop hematological or solid tumors. "In human patients, RAD51 is associated with the dominantly inherited Fanconi anemia, complementation group R (OMIM:617244)." (PMID 40913728, 2025). "The RAD51 T131P mutation, which engenders a Fanconi anemia-like phenotype, negatively impacts the stability of RAD51 nucleoprotein filaments." (PMID 37843130, 2023). "A myriad of mutations in RAD51 paralogs have been associated with Fanconi anemia and various types of cancer." (PMID 37843130, 2023). "Dominant negative mutations in RAD51 protein variants are suggested to be associated with the Fanconi anemia subtype." (PMID 35163785, 2022). "For example, RAD51 mutation has been found to be associated with the disorder in congenital mirror movements and Fanconi anemia." (PMID 35359409, 2022). "Remarkably, using a Fanconi anemia patient cell line harboring one mutant RAD51 allele that is sensitive to PARPi/cisplatin but proficient in HR, they found an increase in ssDNA gaps that can be restored upon conversion of the mutant RAD51 allele to WT." (PMID 36568963, 2022). "While patients with biallelic mutations in RAD51 and its mediators have been identified in patients with Fanconi anaemia, monoallelic germline mutations in RAD51 mediators are correlated to predisposition to cancer." (PMID 36010882, 2022). "Conversely, the Fanconi anaemia-associated dominant-negative RAD51 T131P mutation negatively impacts the stability of the RAD51 nucleoprotein filament, thereby abrogating replication fork protection, while maintaining HR proficiency." (PMID 32938550, 2021). "Mutations in the human RAD51 paralogs are associated with multiple types of cancer and diseases such as Fanconi Anemia." (PMID 34573372, 2021). "Here the authors report a de novo mutation in the DNA repair gene Rad51 in an atypical subtype of Fanconi anaemia." (PMID 26681308, 2015). "Of note here is that RBS fibroblasts were less sensitive to MMC than fibroblasts from a PALB2 deficient Fanconi anemia patient, which has a more general defect in crosslink repair and shows a disturbance in the formation of Rad51 foci." (PMID 19738907, 2009). "Spearman correlation analysis revealed a significant positive correlation (p < 0.05) between RAD51 expression and genes within multiple chemotherapy resistance‐associated pathways, including the Fanconi anaemia pathway, homologous recombination and platinum drug resistance." (PMID 41350246, 2025). "Additionally, significant roles are played by PALB2, ATM, ATR, CHEK1, CHEK2, RAD51, and genes linked to Fanconi anaemia." (PMID 40069561, 2025). "Molecular pathogenesis may provide insight into the link between the molecular defect and the discrete phenotypes related to human RAD51 mutations, namely, atypical Fanconi anemia (FA-R), premature ovarian insufficiency, and CMM." (PMID 37190078, 2023). "Mutations in RAD51C and XRCC2 are associated with Fanconi Anemia, which causes bone marrow failure and a predisposition to leukemia and solid tumors, and mutations in all RAD51 paralogs have been associated with multiple types of cancer including mostly breast and ovarian cancers." (PMID 34573372, 2021). "Rad51 paralogs play a crucial role in regulating proper levels of HR, and mutations in the human counterparts have been associated with diseases such as cancer and Fanconi Anemia." (PMID 34573372, 2021). "Considerable evidence is now available suggesting that loss of one or several key genes involved in HR, among these ATM, CHEK1/2, NBN, RAD51 and genes of the Fanconi Anemia complementation group, is associated with sensitivity of cancers to platinum drugs and PARP inhibitors." (PMID 27756336, 2016).
Fanconi anemia (continued). "Clinically, HRR defects extend beyond BRCA1/2, encompassing PALB2, BARD1, RAD51 paralogs and Fanconi anemia genes; RAD51 foci assays are emerging as functional biomarkers to guide PARP inhibitor use and combination strategies." (PMID 41373427, 2025). "Among these genes were members of the Fanconi anemia (FA) core complex (Fanca, Fancc, and Fancl), Rad51, Mlh1, Atrip, and Rfc2; all were expressed at significantly higher levels in Ncf1–/– vs. WT NSCs." (PMID 36707536, 2023). "Another group of proteins, whose chromatin association was affected upon SLF2 loss belongs to regulators of DDR, such as components of the Fanconi anemia repair pathway and the RAD51‐mediated HR machinery." (PMID 37485814, 2023). "Since RAD51 can be over expressed in tumors and pathogenic variants of RAD51 have been reported in an atypical form of FA (FA-R), investigating the potential interplay between R-loops, RAD51, and cancer progression or Fanconi anemia should be informative." (PMID 37190078, 2023). "RAD51-T131P, a dominant negative form of RAD51 found in a patient with Fanconi anemia, is also defective for DNA binding in living cells." (PMID 35137208, 2022). "Upregulation of the fanconi anemia pathway components such as RAD51 and BRCA1/2, leads to homologous recombination restoration and drug resistance." (PMID 35874683, 2022). "Fanconi anemia (FA, MIM 607,139) is a rare autosomal recessive, X-linked (FANCB) or autosomal dominant (FANCR/RAD51) bone marrow failure disease, which occurs at a rate of 1–5 cases per million." (PMID 36167633, 2022). "Like the BRCA2–RAD51 axis, also the Fanconi Anemia (FA) components FANCB and FANCD2 suppress MRE11-mediated fork degradation in a way linked to RAD51 protein." (PMID 35681784, 2022). "It abolishes the recruitment of RAD51 at stalled forks in Fanconi anemia cells, thereby exposing the stalled forks to the nucleases MRE11 and DNA231." (PMID 35768579, 2022). "RAD51 is a member of the Fanconi anemia repair pathway, and is dependent, in Wnt-high cancers, on Wnt/β-catenin signaling." (PMID 36364346, 2022). "Fanconi anemia proteins are involved in a series of functions during homology-directed repair including stabilization of RAD51 on ssDNA." (PMID 34946909, 2021). "Here, we catalogue the dysregulations of HR genes in human pathologies, including cancer and Fanconi anaemia or congenital mirror movement syndromes, and we discuss the RAD51 paradox." (PMID 34316706, 2021). "Traditional HR is a Rad51-dependent pathway that uses double-stranded DNA (dsDNA) as a template, while single-stranded template repair (SSTR) is Rad51-independent and uses the Fanconi anemia (FA) DNA repair pathway." (PMID 32466470, 2020). "qRT-PCR data confirmed that the expression of Fanconi anemia-associated genes including BRCA1, BRCA2, PALB2, and RAD51 and cancer-associated genes (ALDH1A3 and IGF1R) was strongly inhibited by FR treatment, as shown by microarray analysis." (PMID 30719229, 2019). "As RAD51 is the downstream effector protein of the Fanconi anemia-BRCA pathway (FA-BRCA) which mediates HR, we further analyzed BRCA1 levels in these cells." (PMID 31492187, 2019). "Deficiency in several of the classical human RAD51 paralogs [RAD51B, RAD51C, RAD51D, XRCC2 and XRCC3] is associated with cancer predisposition and Fanconi anemia." (PMID 31584931, 2019). "Proteins other than BRCA2 implicated in homologous recombination or the Fanconi anemia repair pathway, like BRCA1, RAD51, PALB2, XRCC3, FANCI, or FANCD2, were at most modestly affected, as were non-homologous end joining proteins like KU80, KU70, and XRCC4." (PMID 28575672, 2017). "Large T-antigen also induced apparent DNA damage as measured by COMET assay, the Fanconi anemia pathway and Rad51 foci." (PMID 28202068, 2017). "Another advantage for testing RAD51 and FANCD2 was that these protein foci formations require other upstream proteins, such as five RAD51 paralog proteins and eight Fanconi anemia proteins." (PMID 27257868, 2016).